ELP3 (elongator acetyltransferase complex subunit 3)
Diseases named in the same sentence as ELP3 in open-access papers (continued):
Sharing a sentence is not in itself a finding about the gene and the disease.
intestinal tumors (1 paper, 2022). "Although the role of Elp3 in all stromal cells remains to be extensively defined, our data strengthen the notion that Elp3 is a promising therapeutic target to treat intestinal tumors showing constitutive Wnt signaling." (PMID 35920020, 2022). "We also demonstrate that Elp3 expression in myeloid cells is required in Wnt‐driven tumor development in the intestine, at least by maintaining the pool of infiltrated M2‐like macrophages in intestinal tumors." (PMID 35920020, 2022).
invasive breast carcinoma (1 paper, 2018). A carcinoma that infiltrates the breast parenchyma. "Furthermore, genetic ablation of ELP3 strongly impaired invasion and metastasis formation in a model system of invasive breast cancer." (PMID 30597914, 2018). "In detail, ELP3 and CTU1•CTU2 are upregulated in human invasive breast cancer and support cellular invasion through the translation of the DEK oncoprotein, which subsequently promotes the IRES (internal ribosome entry site)-dependent translation of the pro-invasive transcription factor LEF1." (PMID 30597914, 2018).
leukemia (1 paper, 2024). A malignant (clonal) hematologic disorder, involving hematopoietic stem cells and characterized by the presence of primitive or atypical myeloid or lymphoid cells in the bone marrow and the blood.
metastatic melanoma (1 paper, 2024). A melanoma that has spread from its primary site to another anatomic site. "Multiple studies defined Elp3 as a promising target to fight against a variety of epithelial malignancies as well as metastatic melanomas." (PMID 39085648, 2024).
tongue tumors (1 paper, 2017). "Pcna and Elp3 mRNA levels were significantly upregulated in tongue tumors from DOX+ iDek mice compared with those from DOX‐ iDek mice." (PMID 28834425, 2017).
ulcerative colitis (1 paper, 2022). An inflammatory bowel disease involving the mucosal surface of the large intestine and rectum. "In agreement with the notion that Elp3 deficiency is linked to an increased inflammatory status, patients suffering from ulcerative colitis showed lower levels of both Elp1 and Elp3." (PMID 35920020, 2022).
viral infection (1 paper, 2025). "Importantly, ELP3 was also necessary for innate immune gene induction following virus infection." (PMID 41203129, 2025). "However Elp3−/− cells upregulated Ccl5 to levels comparable with WT cells following PR8 viral infection, so not all host innate gene induction responses to IAV were Elongator-dependent." (PMID 41203129, 2025).
cancer (13 papers, 2017 to 2026). A tumor composed of atypical neoplastic, often pleomorphic cells that invade other tissues. "To understand how these mutations affect Elongator activity, we analyzed ALS-related (R454K, R473K) and cancer-related (I298S, R242K, R402T, and D443N) variants of human ELP3." (PMID 38750017, 2024). "Notably, dysregulation of the tRNA modification activity of Elp3 is associated with various human diseases, including various cancers and neurodegenerative diseases, and Elp2 also participates in the regulation of these diseases." (PMID 41501031, 2026). "In intestinal epithelial cells, the Wnt signaling pathway can upregulate Elp3 expression, promote Sox9 protein expression, and maintain cancer stem cell subpopulations." (PMID 41501031, 2026). "Taken together, we elucidate a new function of ELP3 in promoting tumorigenesis by stabilizing c-Myc, suggesting that inhibition of ELP3 is a potential strategy for treating c-Myc-driven carcinomas." (PMID 37771073, 2024). "Elongator-dependent tRNA modifications are also dysregulated in cancers with elevated ELP3 expression, such as WNT-dependent colon cancer, breast cancer and BRAFV600E melanoma." (PMID 32298235, 2020). "A Wnt-dependent up-regulation of Elp3 has been detected in intestinal epithelia cells, where it promotes the expression of the Sox9 protein, which is critical to maintain the cancer stem cell subpopulation." (PMID 33152999, 2020). "Some of the drugs we have tested here in relation to the status of elp3 and dph genes are frequently used in cancer chemotherapy." (PMID 28775286, 2017). "In this study, we found the new mechanism of c-Myc regulation and provided evidence that ELP3 may be a potential therapeutic target for c-Myc-driven carcinomas." (PMID 37771073, 2024). "Along with epigenetic modifiers that were previously implicated in cancer cell fitness, such as CHD1, CHD4, DNMT3B, ELP3, SUPT16H, SUV39H2; novel hits ASH2L, RBX1 and SSRP1 were discovered as essential genes for both U373 and T98G cells suggesting common regulatory role." (PMID 37974198, 2023). "In these cancers, ELP3-mediated tRNA modification directs a codon-specific translational programme." (PMID 32298235, 2020). "Last but not least, ELP3 has been shown to be overexpressed in human cancer cells and the function of Elongator promotes cancer cell survival during therapy relapse." (PMID 38750017, 2024). "This analysis found that, compared to NATs, cancer cells can in general tolerate to a greater degree the genomic deletion of KATs compared to NATs, with a small fraction of highly essential enzymes (e.g., TAF1 and ELP3)." (PMID 32942614, 2020).
tumor (13 papers, 2016 to 2024). "ELP3, the catalytic subunit of the Elongator complex, is an acetyltransferase and associated with tumor progression." (PMID 37771073, 2024). "Accumulating lines of evidence show that ELP3 is closely associated with tumor progression." (PMID 37771073, 2024). "Whether ELP3 deficiency can influence tumor progression by impairing T-cell activation remains undetermined." (PMID 38476632, 2024). "As Elp3 controls M2 macrophage polarization, we next assessed whether Elp3 deficiency in myeloid cells had any consequences on Wnt‐driven tumor development in the intestine." (PMID 35920020, 2022). "Therefore, Elp3 deficiency in myeloid cells delays tumor development upon constitutive Wnt signaling, at least by negatively impacting on the pool of TAMs." (PMID 35920020, 2022). "Finally, Elp3 deficiency in myeloid cells delays Wnt‐driven tumor initiation in the intestine by altering the pool of tumor‐associated macrophages (TAMs)." (PMID 35920020, 2022). "In this study, we investigated the role of ELP3, involving the regulation of c-Myc stability, in tumor progression." (PMID 37771073, 2024). "ELP3’s impact extends to WNT-driven tumor development in the intestine by sustaining a pool of M2-like macrophages within tumors." (PMID 38476632, 2024). "The importance of ELP3 in tumor progression is indicated by aberrant overexpression of ELP3 in a wide range of human tumors and the fact that ELP3 depletion abolishes tumor formation in Wnt-driven mouse model." (PMID 37771073, 2024). "It is reported that ELP3 is an acetyltransferase and engaged in multiple processes of tumor progression, including resistance to apoptosis, cell proliferation, and stemness." (PMID 37771073, 2024). "Our findings uncover the mechanism of ELP3-mediated regulation of c-Myc stability in tumor progression." (PMID 37771073, 2024). "Lastly, the genetic inactivation of Elp3 in myeloid cells delays Wnt‐driven tumor initiation in the intestine." (PMID 35920020, 2022). "This delay in tumor development also occurs when Elp3 is inactivated in intestinal epithelial cells." (PMID 35920020, 2022). "Elp3 expression in epithelial cells promotes Wnt‐driven tumor initiation in the intestine and breast cancer metastasis, at least by promoting the expression of Sox9 and DEK in a codon‐dependent manner, respectively." (PMID 35920020, 2022). "Elp3 expression in myeloid cells further promotes Wnt‐driven tumor initiation in the intestine by maintaining a pool of tumor‐associated macrophages exhibiting M2 features." (PMID 35920020, 2022). "However, little is known about the carcinogenic function of ELP3 other than acetyltransferase in tumor progression." (PMID 37771073, 2024). "However, little is known about the function of ELP3 other than acetyltransferase in tumor progression." (PMID 37771073, 2024). "Previous studies provided evidence that ELP3 is involved in tumor progression." (PMID 37771073, 2024). "Given that ELP3-mediated regulation of c-Myc and the function of c-Myc in metabolic reprogramming, we therefore explored whether ELP3 plays a role in tumor metabolism." (PMID 37771073, 2024). "Xenograft assay showed that ELP3 knockdown extensively diminished tumor size." (PMID 37771073, 2024). "The underlying hypothesis for this decrease could be explained by the effect of therapeutic procedure on tumor size and, therefore, decline in Circ‐ELP3 expression and excretion from tumor cells." (PMID 34545638, 2021). "While Elp3 was found to be the catalytic subunit of the Elongator protein complex, Elp3 expression is induced by Wnt signalling and is essential for Wnt-driven tumour development in the intestine." (PMID 27974624, 2016). "Loss of 8p involving the DLC1, CCDC25, ELP3, PROSC, SORBS3, SH2D4A genes associated with poor outcomes for HCC; in vitro and in vivo analysis indicated that the PROCS, SH2D4A and SORBS3 genes have tumor-suppressive activities and the DLC1 gene is a known tumor suppressor gene." (PMID 34103027, 2021).
tumor (continued). "Thus, our findings provide a specific molecular pathway via which ELP3, the catalytic subunit of Elongator, may accomplish this tumor suppressor function." (PMID 29497044, 2018). "Knockdown of ELP3 inhibits the oncoprotein DEK translation, which reduced LEF1 IRES-dependent translation and tumor invasion." (PMID 37771073, 2024). "As described, epigenetic modification of tRNA (U34) further supports tumorigenesis by up-regulating U34 enzymes and enhancing codon wobble of especially tumor promoting genes, an effect that prominently involves SRY-box 9 (SOX9) and elongator complex protein 3 (Elp3)." (PMID 30921315, 2019). "Independent of FD, the Elongator subunit ELP3 has also been characterized as a tumor suppressor gene in studies correlating diminished ELP3 levels with a poor prognosis in cancer." (PMID 29497044, 2018).
neurodegenerative disease (4 papers, 2010 to 2024). A disorder of the central nervous system characterized by gradual and progressive loss of neural tissue and neurologic function. "This study provides a framework for further investigation that will clarify mechanistic insights into mt-ELP3 in the mt-tRNA modification reaction and the contributions of its defect in neurodegenerative diseases." (PMID 36045139, 2022). "The correlation between ELP3 expression, tRNA modification (specifically mcm5s2U), and the solubility of mutant SOD1 proteins emphasizes the importance of ELP3-mediated tRNA modifications in understanding neurodegenerative disease mechanisms." (PMID 39061374, 2024).
infection (3 papers, 2022 to 2025). The state of being infected such as from the introduction of a foreign agent such as serum, vaccine, antigenic substance or organism. "Elp3 deficiency impaired tuft cell amplification post-infection, as evidenced by anti-Dclk1 immunofluorescence (IF) analyses." (PMID 39085648, 2024). "Of note, IL-13Rα1 but not IL-4Rα mRNA levels were decreased upon Elp3 deficiency 7 days post-infection." (PMID 39085648, 2024). "RSV-mediated induction of type I IFNs was undetectable following infection of either WT and Elp3−/− cells (data not shown), likely due to immune evasion strategies employed by the virus." (PMID 41203129, 2025). "Moreover, mRNA levels of a variety of receptors known to be expressed by tuft cells did not increase in IECs lacking Elp3 at day 7 post-infection." (PMID 39085648, 2024).
neurologic diseases (3 papers, 2013 to 2025). "More recent evidence demonstrates that disruptions in ELP3-mediated microtubule acetylation are a common feature in multiple neurological disorders, presenting ELP3 action as a potential target for acetylation-based therapeutic interventions." (PMID 40558500, 2025).
ELP3 also shares sentences with these, for which no sentence is quoted: motor neuron disease (2 papers); Rolandic epilepsy (2); asthma (1); autism spectrum disorder (1); bile duct cancer (1); Cognitive impairment (1); frontotemporal lobar degeneration (1); invasive ductal breast carcinoma (1); lung carcinoma (1); lymphoma (1); microcephaly (1); ovarian carcinoma (1); Prader-Willi syndrome (1); septic shock (1); tongue SCC (1); triple-negative breast carcinoma (1).